WDR26 (WD repeat domain 26)
Description:
G-beta-like protein involved in cell signal transduction. Acts as a negative regulator in MAPK signaling pathway. Functions as a scaffolding protein to promote G beta:gamma-mediated PLCB2 plasma membrane translocation and subsequent activation in leukocytes. Core component of the CTLH E3 ubiquitin-protein ligase complex that selectively accepts ubiquitin from UBE2H and mediates ubiquitination and subsequent proteasomal degradation of the transcription factor HBP1. Acts as a negative regulator of the canonical Wnt signaling pathway through preventing ubiquitination of beta-catenin CTNNB1 by the beta-catenin destruction complex, thus negatively regulating CTNNB1 degradation. Serves as a scaffold to coordinate PI3K/AKT pathway-driven cell growth and migration. Protects cells from oxidative stress-induced apoptosis via the down-regulation of AP-1 transcriptional activity as well as by inhibiting cytochrome c release from mitochondria. Also protects cells by promoting hypoxia-mediated autophagy and mitophagy (By similarity).
Synonyms: CDW2; MIP2; FLJ21016; GID7; SKDEAS
Tractability: Small molecule: a structure with a bound ligand is known. PROTAC: ubiquitination databases record sites on it; its protein half-life has been measured.
Target class: Reader; Epigenetic regulator; Methyl-lysine/arginine binding protein; WDR domain
Gene: Protein-coding gene on chromosome 1 (224,385,146 to 224,437,033, reverse strand). Ensembl gene ENSG00000162923.
Subcellular location: Cytoplasm; Nucleus; Mitochondrion
Subcellular location (Human Protein Atlas): Cytosol; Nucleoplasm; Mitochondria
Pathways (Reactome):
Metabolism: Regulation of pyruvate metabolism
Gene Ontology:
Molecular function: protein binding
Biological process: proteasome-mediated ubiquitin-dependent protein catabolic process
Cellular component: cytoplasm; cytosol; nucleoplasm; nucleus; ubiquitin ligase complex; GID complex; mitochondrion
Genetic constraint (gnomAD): Loss-of-function variants: 5 observed, 73.03 expected, observed/expected ratio (o/e) 0.0685, 90% interval 0.035 to 0.14. The upper end of that interval is the gene's LOEUF score, 0.14, which puts it in group 1 of 6, group 1 being the genes least tolerant of losing a copy. Missense variants: 636 observed, 913.15 expected, observed/expected ratio (o/e) 0.7, 90% interval 0.65 to 0.74. Synonymous variants: 411 observed, 367.03 expected, observed/expected ratio (o/e) 1.12, 90% interval 1.03 to 1.22.
Gene-disease validity (ClinGen):
ClinGen rates the evidence that WDR26 causes each of these diseases.
Skraban-Deardorff syndrome (autosomal dominant): Definitive.
Homologues: Orthologues: pig WDR26 (99% identical), rat Wdr26 (92% identical), chimpanzee WDR26 (87% identical), macaque WDR26 (87% identical), dog WDR26 (84% identical), mouse Wdr26 (83% identical), rabbit WDR26 (73% identical), zebrafish wdr26b (67% identical), guinea pig WDR26 (66% identical), tropical clawed frog wdr26 (63% identical), zebrafish wdr26a (56% identical), Drosophila melanogaster CG7611 (42% identical). Paralogues in human: WDR13 (15% identical).
Diseases named in the same sentence as WDR26 in open-access papers:
WDR26 is named in the same sentence as 38 diseases in open-access papers, as found by Europe PMC text mining. Sharing a sentence is not in itself a finding about the gene and the disease. The quoted sentences say what the papers report.
breast carcinoma (11 papers, 2016 to 2024). "Upregulation of WDR26 has been linked with the onset of breast cancer and poor survival rate of breast cancer patients." (PMID 39872503, 2024). "Analysis of possible targets for miR-29b-1-5p reveals that the top 4 targets, USP28, NEUROD1, LIN9 and WDR26 have all been previously associated with breast cancer." (PMID 30323900, 2018). "Through bioinformatic analysis, we also noticed that the WDR26 gene had the highest copy number in breast cancer samples." (PMID 39872503, 2024). "It has been reported that WDR26 is upregulated in malignant breast tumors, and the upregulation of WDR26 facilitated the growth and metastasis of breast cancer by stimulating the activation of PI3K/AKT pathway." (PMID 32847606, 2020). "The physical and functional interaction between the two TROLLs and WDR26 is particularly significant for basal-like breast cancers and melanomas, where high levels of these lncRNAs as well as high levels of TROLL-3 and WDR26 correlate with poor prognosis." (PMID 33056990, 2020). "That investigation showed that WDR26 overexpression correlates with shortened survival of breast cancer patients." (PMID 31885576, 2019). "In breast cancer cells, WDR26 fosters assembly of a specific signaling complex consisting of Gβγ, PI3-kinase, and AKT2." (PMID 31885576, 2019). "Together, our results identify a novel mechanism regulating GPCR-dependent activation of the PI3K/AKT signaling axis in breast tumor cells, and pinpoint WDR26 as a potential therapeutic target for breast cancer." (PMID 26895380, 2016). "In breast cancer cells, downregulation of WDR26 selectively impaired GPCRs from inducing AKT phosphorylation via Gβγ, but did not prevent RTKs from signaling for growth factor-mediated AKT activation." (PMID 26895380, 2016). "Our data argue that WDR26 promotes breast cancer growth and metastasis through the GPCR-mediated PI3K/AKT signaling pathway." (PMID 26895380, 2016). "Together, these findings indicate that WDR26 selectively promotes GPCR-stimulated breast cancer cell growth, migration and invasion." (PMID 26895380, 2016). "Together, these findings indicate that WDR26 promotes breast cancer growth and migration primarily through the PI3K/AKT pathway." (PMID 26895380, 2016). "We therefore postulated that WDR26 similarly regulates PI3K/AKT activation in breast cancer cells by fostering the interactions between Gβγ, PI3K and AKT." (PMID 26895380, 2016). "In an orthotopic xenograft mouse model of breast cancer, disrupting formation of this complex, by overexpressing WDR26 mutants in MDA-MB231 cells, abrogated PI3K/AKT activation and tumor cell growth and metastasis." (PMID 26895380, 2016). "Increased WDR26 expression in samples of malignant cancers at the protein level was verified immunohistochemically by comparing breast cancer tissues (stage II and III) to matched, adjacent, normal breast tissues." (PMID 26895380, 2016). "To confirm further that WDR26 plays an important role in breast cancer cell growth, migration and invasion, we examined the effects of ectopic WDR26 expression in MCF7 cells, which only express a low level of endogenous WDR26." (PMID 26895380, 2016). "In this study, we identified WDR26 as a novel regulator of the PI3K/AKT pathway, and showed that aberrant expression of WDR26 in breast cancer cells contributes to breast cancer cell growth and metastasis." (PMID 26895380, 2016). "To probe how WDR26 regulates GPCR signaling in breast cancers, we examined the effect of WDR26 downregulation on the activation of Gα- or Gβγ-mediated signaling pathways downstream of GPCR stimulation." (PMID 26895380, 2016). "Compared to normal breast tissues, breast cancer cells (from the TCGA invasive dataset, Cell, 2015) expressed significantly more WDR26 mRNA." (PMID 26895380, 2016). "Compared to non-transformed MC10A cells, in MDA-MB231 and DU4475 cells (two highly metastatic breast cancer cell lines) WDR26 was overexpressed by 1.5 to 2 fold." (PMID 26895380, 2016).
breast carcinoma (continued). "Moreover, we demonstrate that knockdown of PTPN21 or WDR26 effectively inhibits the growth of breast cancer cells." (PMID 39872503, 2024). "Because the lncRNAs are prognostic factors in breast cancer progression and their levels correlate with those of WDR26, we assessed whether the combination of either lncRNA with WDR26 may be prognostic in breast cancer." (PMID 33056990, 2020). "To test this, we first determined whether WDR26 is localized in the cytoplasm in the MCF10A breast cancer progression model." (PMID 33056990, 2020). "Meanwhile, in target genes-miRNA network (down regulated), WDR26 was responsible for the invasion of breast cancer cells, but this gene may be identified with invasion of GBM." (PMID 31137733, 2019). "Collectively, these results identified WDR26 as a potential therapeutic target for breast cancer." (PMID 31885576, 2019). "Since inhibiting WDR26 blocks breast cancer cell migration in vitro and metastasis in vivo, targeting WDR26 may also represent a novel approach for the treatment of both primary and metastatic tumors." (PMID 26895380, 2016). "Because we had access to only a limited number of clinical samples and cell lines, it remains to be determined whether WDR26 expression correlates with particular breast cancer subtypes or histological features." (PMID 26895380, 2016). "To examine how changes in PI3K activation might contribute to WDR26-regulated breast cancer cell growth and migration, we determined the effect of specific PI3K inhibitors on the enhanced MCF7 cell growth and migration induced by WDR26 overexpression." (PMID 26895380, 2016). "Together, our results define an unknown mechanism of regulating GPCR-dependent activation of the PI3K/AKT signaling axis in breast tumor cells, and identify WDR26 as a potential novel target against breast cancer." (PMID 26895380, 2016). "Here, we demonstrate that WDR26 is overexpressed in highly malignant breast tumor cell lines and human breast cancer samples, and that WDR26 overexpression correlates with shortened survival of breast cancer patients." (PMID 26895380, 2016). "In summary, we demonstrated that WDR26 is overexpressed in highly malignant breast cancer cells and patient samples, and upregulated WDR26 overactivates the Gβγ-mediated PI3K/AKT pathway downstream of multiple GPCRs, promoting breast cancer cell growth, migration and invasion." (PMID 26895380, 2016). "Importantly, WDR26 overexpression correlated with shorter patient survival, suggesting WDR26 may be an important regulator or prognostic marker of breast cancer progression." (PMID 26895380, 2016). "WDR26 was over-expressed in malignant breast tumors, resulting in PI3K/Akt pathway activation and further progression and spread of breast cancer." (PMID 37854681, 2023). "Together, these data indicate that during breast cancer progression, the levels of TAp63 are reduced while those of TROLL-2 and TROLL-3 increase, and this correlates with the cytoplasmic localization of WDR26." (PMID 33056990, 2020). "In line with our observations in breast cancer, all the malignant tumour types assessed had increased levels of TROLL-2, TROLL-3 and WDR26 compared to normal tissue and benign lesions." (PMID 33056990, 2020). "Our results also suggest WDR26 integrates interactions between Gβγ, PI3Kβ, and AKT2, which is critical for Gβγ-mediated PI3K/AKT signaling and function in breast cancer cells." (PMID 26895380, 2016). "WDR26, a WD40 protein that is overexpressed in highly malignant breast cancers and is associated with poor survival of breast cancer patients, selectively bound to Akt2 and not Akt1." (PMID 34298660, 2021). "In addition, we found that the expression of both WDR26 and NCOA5 increased over the progression of breast cancer and were enriched in highly aggressive and poorly differentiated grade three tumours compared with grade 1 and 2 cases." (PMID 33056990, 2020).
breast carcinoma (continued). "Furthermore, downregulating WDR26 levels by siRNAs (targeting two distinct coding regions of WDR26) reduced the size of MDA-MB231 cell colonies in Matrigel by 50%, demonstrating that WDR26 promotes breast cancer cell proliferation." (PMID 26895380, 2016). "Thus, overexpression of WDR26 N-terminal truncation mutants, WDR123-661 and WDR295-661, blocks AKT activation and breast cancer cell growth and migration in vitro and in vivo." (PMID 26895380, 2016). "This would explain why WDR26 mutants lacking N-terminal domains are dominant negative inhibitors of breast cancer growth and migration." (PMID 26895380, 2016). "Intriguingly, it was recently reported that lncRNAs (TROLL-2 and TROLL-3) could counteract the interaction between WDR26 and NOLC1, while promoting the combination of WDR26 and AKT to activate the PI3K/AKT pathway in lung cancer cells, human breast carcinoma cells, and human melanoma cell lines." (PMID 34046062, 2021). "Given the correlation between high expression of TROLL-2 and TROLL-3, WDR26 localization, and AKT phosphorylation in DCIS derived tumours, we tested whether such correlation was also present in the breast cancer TMAs that we assessed for the ISH of TROLL-2 and TROLL-3 and the IHC of WDR26." (PMID 33056990, 2020). "Importantly, when we examined the localization of WDR26 in the TMA of breast cancer progression based on the ISH score of TROLL-2 and TROLL-3, we found that high levels of these two lncRNAs correlated with high levels and cytoplasmic localization of WDR26." (PMID 33056990, 2020). "Given that the WDR26 fragments, WDR123-661 and WDR295-661, could still interact with AKT2 and PI3Kβ, we reasoned that they might also interfere with the function of the full-length WDR26 in breast cancer cells." (PMID 26895380, 2016). "Interestingly, although WDR26 selectively regulates PI3Kβ and AKT2 signaling, its activity on breast cancer cell growth and migration does not seem to depend on the status of PI3Kα mutation, PTEN expression or RTK overexpression." (PMID 26895380, 2016).
Intellectual disability (9 papers, 2021 to 2026). "Skraban-Deardorff syndrome, a rare neurodevelopmental disorder caused by WD repeat domain 26 (WDR26) haploinsufficiency, is characterized by intellectual disability, seizures, autistic-like behaviors, and craniofacial anomalies." (PMID 42138082, 2026). "One novel de novo fame-shift variant was identified in the WDR26 gene, and WDR26 haploinsufficiency has been linked to a syndrome characterized by intellectual disability, seizures, abnormal gait, and distinctive facial features." (PMID 34055682, 2021). "The pathogenic mutations of its paralogue—WDR26—lead to well-recognized intellectual disability (Scraben-Deardorff syndrome, OMIM#617616), demonstrating an overlap with the phenotype of our patient." (PMID 34946860, 2021). "Interestingly, mutations of the CTLH complex component WDR26 (the most significant pT217 tau interactor) lead to intellectual disability, seizures and other neurological and developmental issues, suggesting that WDR26 has a fundamental role in brain development." (PMID 40317322, 2025). "WDR26 and FBXO28 are located within the 1q41-q42 deletion syndrome critical region, a rare cause of intellectual disability, seizures, facial dysmorphia, and multiple anomalies." (PMID 36980980, 2023). "LisH proteins, which are known to form CTLH E3 ligase complex, are enriched in Skraban Deardorff syndrome, also known as WDR26-related intellectual disability disorder, characterized by developmental delays, seizures, intellectual disability, and neurological symptoms." (PMID 41312386, 2025).
Skraban-Deardorff syndrome (5 papers, 2022 to 2026). "In this study, we describe two additional cases of patients with Skraban-Deardorff syndrome who had two de novo heterozygous mutations in the WDR26 gene (NM_025160.7; c.1797delC(p.His599fs*11), c.1414C>T(p.Gln472*))." (PMID 39363971, 2024). "To date, only 28 loss-of-function (LoF) WDR26 mutations have been identified in patients with Skraban-Deardorff syndrome." (PMID 39363971, 2024). "In this study, We report two unrelated Chinese patients with Skraban-Deardorff syndrome caused by novel de novo pathogenic variants of the WDR26 gene." (PMID 39363971, 2024). "The mechanism by which a haplotype deficiency of the WDR26 gene leads to Skraban-Deardorff syndrome remains a mystery." (PMID 39363971, 2024). "Skraban-Deardorff syndrome is a rare autosomal dominant genetic disease caused by variants in the WDR26 gene." (PMID 35627197, 2022). "The pattern of widespread expression of WDR26 in human tissues suggests that mutations in the WDR26 gene may be responsible for the widespread and heterogeneous phenotype of Skraban-Deardorff syndrome." (PMID 39363971, 2024). "Here, two novel de novo variants (c.1797delC(p.His599fs*11) and c.1414C>T(p.Gln472*)) in the WDR26 gene have been identified in two Chinese patients with Skraban-Deardorff syndrome." (PMID 39363971, 2024). "Patients with Skraban-Deardorff syndrome (SKDEAS), a neurodevelopmental syndrome associated with a spectrum of developmental and intellectual delays and disabilities, harbor diverse mutations in WDR26, encoding a subunit of the multiprotein CTLH E3 ubiquitin ligase complex." (PMID 38575527, 2024). "In this study, two unrelated Chinese patients were diagnosed with Skraban-Deardorff syndrome after whole-exome sequencing (WES) analysis revealed two novel de novo WDR26 gene variants." (PMID 39363971, 2024).
depression (2 papers, 2015 to 2019). "Remarkably, one of these DMPs (cg01122889) was located in the WDR26 gene, the DNA sequence of which has been implicated in major depressive disorder from genome-wide association studies." (PMID 25918994, 2015). "Expression of WDR26 has also been proposed as a biomarker of depression in human blood." (PMID 25918994, 2015).
epilepsy (2 papers, 2021 to 2024). A brain disorder characterized by episodes of abnormally increased neuronal discharge resulting in transient episodes of sensory or motor neurological dysfunction, or psychic dysfunction. "From the current study, four variants were located in the epilepsy-related genes, the DPYD gene, NF1 gene, and WDR26 gene." (PMID 34055682, 2021).
invasive breast carcinoma (2 papers, 2016 to 2020). A carcinoma that infiltrates the breast parenchyma. "Compared to less malignant and non-invasive cell lines, such as MCF7 and T47D, highly malignant and invasive breast cancer cell lines (i.e, MDA-MB231 and DU4475) expressed significantly more WDR26." (PMID 26895380, 2016).
melanoma (2 papers, 2020 to 2021). A malignant, usually aggressive tumor composed of atypical, neoplastic melanocytes. "Altogether, our results indicate that the levels of TROLL-2 and TROLL-3 and the cytoplasmic location of WDR26 are markers of cancer progression in several human tumour types, and that these factors are prognostic in melanoma." (PMID 33056990, 2020).
multiple myeloma (2 papers, 2021 to 2023). "Loss of either WDR26 or MTF2 by genetic ablation significantly impeded the growth of myeloma cells in vitro and in vivo via mouse xenograft assays, extending the survival of the xenografted mice." (PMID 37895228, 2023). "Rigorous clinical and biological validation of these genes led to the discovery of two novel myeloma genes: WDR26 (WD repeat-containing protein 26) and MTF2 (metal response element binding transcription factor 2)." (PMID 34876184, 2021). "Further investigation is needed to unravel the oncogenic networks involving MTF2, PHF19, and WDR26 in myeloma, as this could reveal novel opportunities for targeted molecular treatments and prevention strategies." (PMID 37895228, 2023). "Moreover, a forward genetics screen identified MTF2 and WDR26 as drivers of poor survival rates in multiple myeloma." (PMID 37895228, 2023).
breast tumor (1 paper, 2016). "Our data showed that WDR26 is indeed upregulated in highly malignant breast tumors, and upregulated WDR26 promotes breast tumor growth and metastasis by acting as a scaffold that fosters Gβγ-mediated PI3K/AKT activation." (PMID 26895380, 2016).
cerebral infarction (1 paper, 2020). An ischemic condition of the brain, producing a persistent focal neurological deficit in the area of distribution of the cerebral arteries. "Due to the fact that Wdr26 regulates the mitogen-activated kinase pathway to repress oxidative stress-induced apoptosis, it is possible that miR-550b-2-5p inhibits apoptosis in humans during cerebral infarction." (PMID 32354168, 2020).